NF1 (neurofibromin 1)
Diseases named in the same sentence as NF1 in open-access papers (continued):
Sharing a sentence is not in itself a finding about the gene and the disease.
tumor (continued). "By contrast, putative tumour suppressorfunctions of the other two miRNAs located within the NF1 microdeletion region, encoded by MIR4725 and MIR4733,respectively, have not so far been reported." (PMID 28213670, 2017). "We examined HLA-A/-B/-C, B2M, and PD-L1 expression on thirty-six NF1-associated tumor samples by immunohistochemistry, and correlated these with tumoral CD4+, CD8+, FOXP3+, CD56+, and CD45RO+ lymphocytic infiltrates." (PMID 29137242, 2017). "TERT promoter mutations were frequent in the BRAF, RAS, and NF1 subtypes (ranging from 72% to 83%), while they are rare in Triple-WT (about 7%); in this last tumor subtype, alternative mechanisms (gene amplification) are involved in TERT activation." (PMID 29156643, 2017). "Our evaluation of NF1-associated tumor samples from the same patient showed differences based on tumor histologic subtype, timing, and therapeutic intervention." (PMID 29137242, 2017). "Tumors from 870 patients were grouped according to BRAF,RAS,NF1 mutation or triple‐wild‐type status and correlated with tumor and patient characteristics." (PMID 28267273, 2017). "The pathological significance of sporadic NF1 point mutations, especially putative missense mutations that have been identified in many sporadic tumours, is often unclear." (PMID 28637487, 2017). "The Nf1 gene encodes a tumor suppressor that through RAS-GAP activity, functions as a negative regulator of the RAS pathway." (PMID 29162814, 2017). "This was accompanied by a hotspot activating missense mutation in PTPN11, two inactivating frameshift mutations in the NF1 tumor suppressor gene, and an inactivating frameshift mutation in the ATRX tumor suppressor gene." (PMID 28699883, 2017). "Using targeted resequencing with a custom 900 cancer gene panel, eight somatic mutations among them KRAS and NF1, were identified in the primary tumour." (PMID 28061772, 2017). "Constitutional NF1 missense mutations represent about 15% of all NF1 mutations, but their frequency in sporadic tumours ranges widely from 15 to 71%." (PMID 28637487, 2017). "Somatic NF1 mutations have also been detected in 41–72% of sporadic MPNSTs, showing that NF1 inactivation plays a major role in the development of this tumour type." (PMID 28637487, 2017). "This relative enrichment of CCL5 expression in the mesenchymal subtype, which frequently exhibits loss of function mutations in the NF1 tumor suppressor gene, prompted us to focus on murine models characterized by Nf1 loss." (PMID 28380429, 2017). "NF1 is a tumour suppressor gene; in order for a particular cell to become cancerous, both alleles of a tumour suppressor gene must be mutated." (PMID 28637487, 2017). "TAGLN was shown to be involved in NF1 associated tumor progression via hypo-methylation and subsequent up-regulation and stimulation of MAPK signaling in MPNST." (PMID 29131833, 2017). "We found that HLA-A, -B, and -C were down-regulated in both benign and malignant NF1-associated tumors and tumor-associated Schwann cells compared to normal human Schwann cells, with the lowest expression noted in MPNST cell lines." (PMID 29137242, 2017). "Our classifier is able to detect subtle downstream changes in gene expression as a result of the tumor responding to NF1 loss of function." (PMID 28166733, 2017). "Here, we investigated if treatment of tumor cells derived from NF1 associated MPNST respond to ATRA therapy." (PMID 29131833, 2017). "As such, Nf1 optic glioma mice develop a time-dependent sequence of events, beginning with axonal injury at the tumor site, followed by axonal degeneration, RGC loss (apoptosis), retinal nerve fiber layer thinning, and reduced visual acuity." (PMID 28066715, 2016). "Collectively, this new MPNST model system permits the analysis of somatically-acquired events as well as tumor microenvironment signals that potentially cooperate with Nf1 loss in the development and progression of this deadly malignancy." (PMID 26859681, 2016).
tumor (continued). "NF1 is caused by a spectrum of mutations that affect the NF1 gene, which is a tumor suppressor gene located at chromosome 17q11.2." (PMID 27999334, 2016). "Here, we show that AZD8055 can cooperate with anti-MEK PD0325901 to promote tumor cells regression in two distinct NF1-associated peripheral nerve sheath in vitro 2D and 3D models." (PMID 26840085, 2016). "Mutations in PIK3CA (25.9%), INPP5B (30.8%), SRC (99%) and TSC2 (46.7%) were observed in Tumor #3, and Tumor #4 harbored an NF1 gene mutation (43.5%)." (PMID 27057633, 2016). "We also observed that inactivating mutations in NF1 were associated with shorter BCSS in ER− tumours (HR=2.7, CI=1.3–5.5)." (PMID 27161491, 2016). "One of the applications of mouse Nf1 optic glioma models is to define the mechanisms underlying tumor-associated visual decline." (PMID 28066715, 2016). "We also identified a single sample with a G13D KRAS mutation, intriguingly in a tumor also harboring an NF1 frame-shift mutation." (PMID 27078850, 2016). "These preclinical mouse models suggest that additional genetic changes in NF1-associated PA patients differentially influence tumor growth relevant to the design of future therapeutic strategies." (PMID 28066715, 2016). "This reflects the lack of complete understanding of the biology and pathogenesis of these NF1-associated tumors, including the roles of different cell types within the surrounding tumor microenvironment." (PMID 27517146, 2016). "The mesenchymal GBM predominantly harbors loss/mutations in the NF1 tumor suppressor gene coding for neurofibromin 1 and shows TNF family and NFkB pathways activation and expression of mesenchymal markers such as CHI3L1, CD44, and VEGF." (PMID 27738435, 2016). "All four of the spontaneous MPNSTs and one of the NF1-associated tumors were primary neoplasms and the other NF-1 patient had a recurrent tumor." (PMID 27655679, 2016). "NF1 is caused by inherited or de novo pathogenic variants in the NF1 gene, whereas tumor development requires additional mutation of the other NF1 allele (loss of heterozygosity)." (PMID 27482814, 2016). "Loss-of-function mutations in the NF1 tumor suppressor gene affects mTOR pathway, leading to constitutive activation of mTOR." (PMID 26859683, 2016). "NF1 gene is a tumor suppressor gene that encodes for the neurofibromin protein, a member of the Ras family." (PMID 27597922, 2016). "The tumor suppressor NF1 gene, and its conserved murine homologue Nf1, encode the neurofibromin protein, which is ubiquitously expressed in mammalian cells and necessary for development." (PMID 26000738, 2015). "The disease is caused by mutations in the NF1 gene, which is considered a classical tumor suppressor." (PMID 25885768, 2015). "The genetic factors responsible for OPG development in NF1 are not fully understood, however our experimental model provides a robust context in which to assess possible tumor promotion by loss of the imprinted paternal Grb10 allele." (PMID 26000738, 2015). "The second variant was within the gene NF1 (also a tumor suppressor), which encodes the neurofibromin 1 protein and is a frequently mutated gene in GBM." (PMID 25950952, 2015). "Some studies have suggested a possible novel potential NF1 genotype–phenotype correlation, especially with splice-site mutations associated with an increased tendency to develop neoplasms as CNS gliomas and malignant peripheral nerve sheath tumors." (PMID 26347711, 2015). "A subclonal population marked by a NF1 deletion showed a progressive increase in tumour allele fraction during chemotherapy." (PMID 25710373, 2015).
tumor (continued). "Although somatic inactivation of the wild-type NF1 allele is presumed to be the key step in NF1-associated tumour development, this cannot on its own explain the malignant transformation of benign plexiform neurofibromas to MPNSTs." (PMID 25884485, 2015). "The sequence of the NF1 region containing the constitutive mutation revealed WT NF1 alleles in primary tumor samples, indicating the presence of normal human cells (Fig3B)." (PMID 25810463, 2015). "The different clonal origins indicate that each tumor arises from independent somatic events in the background of germline NF1 mutation." (PMID 26432421, 2015). "Human tumor sequencing databases reveal that the Grb10 and NF1 genes can be co-mutated in diverse tumor histologies." (PMID 26000738, 2015). "NF1 predisposes affected individuals to a number of neoplasms in the central and peripheral nervous systems and other tissues." (PMID 26283963, 2015). "Among the deceased patients, 9 of 31 (29%) had NF1 associated with OPG, and these NF1 patients mostly died long after diagnosis (6/9 in group 3) from tumor progression (5/9) or a second tumor (3/9)." (PMID 26098902, 2015). "Among the genes that are mutated between 5 to 20% in TCGA GBM tumor samples, we found mutations in NF1, SPTA1, TCHH and ATRX genes, although, the other genes like PIK3R1, PIK3CA, RB1, IDH1 and KEL were not mutated in any cell line." (PMID 26496030, 2015). "Pathway analysis suggested that potentially actionable mutations in wild-type tumours, including NF1, KIT and NOTCH1, were spread over various signalling pathways." (PMID 24752294, 2014). "NF-1 is caused by defect in the gene responsible for the production of the protein neurofibromin, a tumor suppressor gene linked to the long arm of chromosome 17." (PMID 25852768, 2014). "NF1-associated tumors were larger at the time of diagnosis, 438.4 cm3 (range: 64–4377cm3), whereas the sporadic tumor volume was 240.6 cm3 (range: 10–1000 cm3)." (PMID 25452937, 2014). "NF1 loss appears to be a critical event in mutagen-induced malignancies beyond the classical NF1-associated tumour types." (PMID 25026295, 2014). "Because NF1 gene product named neurofibromin acts as a negative regulator in Ras signal transduction pathway, mutation in NF1 gene is related to tumor development and results in malignancies." (PMID 24971186, 2014). "In two genetically engineered mouse models of MPNST formation, modeling both sporadic and NF1-associated MPNSTs, Everolimus, or PD-901 treatment alone each transiently reduced tumor burden and size, and extended lifespan." (PMID 24681606, 2014). "Consistent with its biochemical activity as a negative regulator of Ras signaling, JMML and other NF1-associated neoplasms frequently show somatic inactivation or the normal NF1 allele." (PMID 24386979, 2014). "This LOH at the NF1 locus has been found in both benign and malignant tumours associated with germline NF1 mutations." (PMID 25520849, 2014). "It is well known that MPNST associated with NF1 shows a poor response to chemotherapy or radiotherapy and the prognosis with residual tumor or metastasis is dismal." (PMID 24971186, 2014). "Given the potential difficulties of detecting the pathogenic mutation in individuals with clinical features of NF1, the identification of somatic NF1 aberrations in sporadic tumours can also pose a significant challenge." (PMID 25026295, 2014). "PD-901 treatment in the NF1-associated mouse model significantly reduced tumor burden from 20.6 tumors per animal with DMSO treatment to 12.8 tumors per animal with PD-901 treatment (p=0.0002)." (PMID 24681606, 2014).
tumor (continued). "NF1 alterations appear to be associated with resistance to therapy and adverse outcomes in several tumour types." (PMID 25026295, 2014). "While these tumors are found in virtually all patients with NF1, there are huge differences in the tumor burden even within family members with the same NF1 mutation." (PMID 25551830, 2014). "The NF1-associated LOH analysis revealed that LOH was increased in the three tumour types, with 9%, 42% and 97% LOH evident in regions 1, 2 and 3, respectively." (PMID 25365429, 2014). "In the NF1-associated mouse model, the combination of Everolimus and PD-901 significantly decreased tumor burden and size, although tumor grade remained high." (PMID 24681606, 2014). "Further studies are required to elucidate how transgelin upregulation in these cells is implicated in tumor progression in NF1." (PMID 25109740, 2014). "There is some evidence that the NF1 gene product is a tumor suppressor, and when some mutation occurs, an uncontrolled cell proliferation is established." (PMID 25580325, 2014). "Three of these patients tumours were analysed with SNParray that revealed loss of heterozygosity at the NF1 loci in tumour DNA in all investigated cases." (PMID 24466223, 2014). "NGS performed on a tumor sample from a liver biopsy obtained at the time of diagnosis revealed NF1 mutation R1241*, BAP1 truncation (exon 12), and CTNNB1 mutation N387K." (PMID 24931142, 2014). "Efforts to identify genetic modifiers of tumor burden or severity in the NF1 mouse model yielded alleles with modest effects but required sizable, complex breeding schemes." (PMID 25329635, 2014). "In the 2013 “WHO Classification of tumours of soft tissue and bone”, it is defined as the association of NOFs and NF1." (PMID 24965055, 2014). "As such, loss of function mutations in the PTEN and NF1 tumor suppressor genes leads to increased AKT activity and attenuated apoptosis." (PMID 25243094, 2014). "Neurofibromatosis 1 (NF1) is an autosomal dominant disease caused by mutations of the NF1 gene, a tumor suppressor gene, on chromosome 17." (PMID 24936179, 2014). "The field size of the tumor that was treated was substantially larger in NF1-associated tumors as compared to sporadic tumors, 597.9 cc3 (range: 31.5–2325.1 cc3) and 290.9 cc3 (range: 18–486.5 cc3), respectively." (PMID 25452937, 2014). "Aneurysms, stenoses, arteriovenous abnormalities, arterial compression by tumors and tumor invasion have each been reported as types of vascular abnormality associated with NF-1." (PMID 24200148, 2013). "Neurofibromatosis type 1 (NF1) is a dysgenetic complex which is due to a loss of function of the tumor-suppressor gene product neurofibromin located on chromosome 17q." (PMID 23890233, 2013). "Our study demonstrated that the down regulation of miR-193b decreased cell viability, clonogencity, migration, invasion, and tumour formation, which in turn, was associated with increased NF1 and a decrease in ERK phosphorylation." (PMID 23335975, 2013). "We are also grateful to R. Hiesinger, H. Kramer, D. van Meyel, R. Palmer and M. Therrien for additional fly stocks, to Spyros Artavanis-Tsakonas and Doug Dimlich for Exelixis deficiency stocks, and to Eline Beert and Eric Legius for NF1 tumor cell RNAs." (PMID 24278035, 2013). "Our study suggests a novel potential NF1 genotype-phenotype correlation, with NF1 splice-site mutations being associated with an increased tendency to develop neoplasms, mostly composed of CNS gliomas and MPNSTs." (PMID 23244495, 2012). "The product of theNF-1 gene, i.e., neurofibromin, was weakly positive in the tumor cells, suggesting that the tumor was induced by a mutation in the NF-1 gene." (PMID 22824559, 2012). "Pten-regulated pathways have been shown to be major tumor suppressive barriers to PNST progression in Schwann cells in the context of Nf1 loss." (PMID 23319880, 2012).
tumor (continued). "Tumours exhibiting mesenchymal primarily rhabdomyosarcomatous differentiation (Triton tumour) are often associated with NF1." (PMID 23036231, 2012). "We also investigated a putative association between the tumour volume normalized against body weight and the rs2151280 genotype (CC vs. CT and TT genotypes) in the 29 NF1 microdeletion patients." (PMID 23101500, 2012). "A variety of neoplasms have been reported to occur in association with NF1 including optic pathway gliomas, astrocytomas, brainstem gliomas, and malignant peripheral nerve sheath tumors (MPNSTs)." (PMID 22236362, 2012). "The results of this study therefore have important implications for molecular studies of NF1-associated tumor specimens." (PMID 23244685, 2012). "Counter to expectation, our method assigns a positive score to NF1, which is a well-known tumor suppressor gene whose loss in GBM also defines a distinct transcriptional subtype {PMID: 20129251}." (PMID 22962493, 2012). "The somatic type-2 deletion identified in tumor P082-1N in this study has to be considered as a second-hit mutation that leads to the loss of the wild-type NF1 allele." (PMID 21031597, 2011). "It is associated with the mutation of NF-1 gene, a tumor suppressor gene located on chromosome 17q11.2." (PMID 21731277, 2011). "A proclivity to multiple tumors arising in the same subject, and a higher tumor burden per family were the most relevant findings observed in patients affected with the NF1 mutation." (PMID 21838856, 2011). "In the present study, we examined expression of MIA in Nf1-deficient mouse cartilage, in human cutaneous and plexiform neurofibromas and MPNSTs, and in sera of NF1 patients with these tumours." (PMID 21726432, 2011). "Our data indicate that a proclivity to multiple tumors arising in the same subject, and a higher tumor burden per family are the most relevant findings observed in affected patients with the NF1 mutation." (PMID 21838856, 2011). "Often abnormal oncogene expression or tumor suppressor gene deletion (PTEN, NF1 or RB) has been associated with “oncogene induced senescence” (OIS) which can be viewed as a protective mechanism to prevent tumor development." (PMID 21881167, 2011). "The other target genes, FLT3, CSF1R, PDGFRB, AXL and MET showed lower expression levels in the tumor tissue compared to normal tissue except AXL in NF1 associated GIST." (PMID 21171987, 2010). "Stage IVdisease was more common in NF1 patients (15%) than those with sporadic tumours(9%) but NF1 was still associated with a significantly worse 5-year survival ifpatients with stage IV disease were removed from the analysis (33% versus 63%; P = .015)." (PMID 19360115, 2009). "The NF1 gene is a tumour suppressor gene located on chromosome 17 that encodes neurofibromin, a widely expressed negative regulator of intracellular RAS signalling in various tissues." (PMID 19946501, 2009). "This reflects the nature of NF1 as a familialneoplastic trait that predisposes to both benign and malignant tumours." (PMID 19360115, 2009). "The maternal allele is deleted in the tumor tissue as demonstrated by loss of heterozygosity of a microsatellite marker located within the NF1 gene." (PMID 16961930, 2006). "Notably, beyond its classic tumor manifestations, NF1 is also associated with unique forms of vasculopathy." (PMID 41515658, 2026). "In addition, individuals with NF1 have a high risk of developing neoplasms compared to the general population, with an incidence of 10% of cases." (PMID 40402550, 2025).